STAT3 (signal transducer and activator of transcription 3)
Diseases named in the same sentence as STAT3 in open-access papers (continued):
Sharing a sentence is not in itself a finding about the gene and the disease.
tumor (continued). "For instance, EOC tumors have been shown to produce significant levels of interleukin (IL)-6 which trigger recruitment of monocytes from the peripheral blood, and via activation of STAT3, convert these cells into tumor supportive M2 tumor associated macrophages." (PMID 28060758, 2017). "STAT3 constitutive activation is usually associated with tumor promoting." (PMID 29126425, 2017). "This elevated STAT1 response may render tumours susceptible to the re-establishment of immune evasion following selective STAT3 re-activation." (PMID 28276425, 2017). "To assess the translational relevance and clinical significance of our findings, we systematically examined association between FGF19 expression and STAT3 activation in primary tumours from the Cancer Genome Atlas (TCGA) database, and in formalin-fixed, paraffin-embedded or frozen human HCC samples." (PMID 28508871, 2017). "Repressed GPRC5A associates with increased tumor grade and activated STAT3, which may be used as a prognostic marker for tumor progression of HNSCC." (PMID 28270740, 2017). "Therefore, no unified conclusion has been reached on the association between p-STAT3 overexpression and tumor prognosis." (PMID 28797050, 2017). "Thus, re-acquisition of STAT3 activity in MT/Shc2F/2F tumours is associated with the eventual emergence of progressively growing tumours." (PMID 28276425, 2017). "Indeed, IL-17 induces IL-6 production by tumor cells and/or tumor-associated stromal cells, which results in the activation of STAT3, a well-known oncogenic TF, that up-regulates pro-angiogenic factors." (PMID 28708082, 2017). "In general, active Stat3 is associated with tumor cell proliferation." (PMID 29133922, 2017). "The translocation of phosphorylated STAT3 mediates the up-regulation of key genes associated with tumourigenesis and tumour immune evasion, and genetic or epigenetic abnormalities resulting in elevated STAT3 expression/activation have been identified in a number of malignancies." (PMID 28423603, 2017). "The Src homology 2 (SH2) domain-containing protein tyrosine phosphatase 1 (SHP-1), a non-receptor protein tyrosine phosphatase, has been reported as a negative regulator of phosphorylated signal transducer and activator of transcription 3 (STAT3) and linked to tumor development." (PMID 28594363, 2017). "Recent reports indicate that STAT3 may also act as tumor suppressor depending on the mutational background." (PMID 28514737, 2017). "As expected, STAT3 signaling suppression in the tumor compartment in these autologously reconstituted humanized mice showed increased tumor infiltrating lymphocytes and reduction of arginase-1 in the stroma, which were associated with slower tumor growth rate." (PMID 28008146, 2017). "In addition, phosphorylated STAT3 was constitutively expressed in the SCLC tumors in vivo and a very recent report supports a role for IL-6 produced by tumor-associated macrophages in the paracrine activation of STAT3, in SCLC." (PMID 29020964, 2017). "Furthermore, it was reported that in patients with GC, expression of IL-6 and STAT3 was increased in GC tumor tissue and that the level was associated with the TNM stage of GC." (PMID 28558708, 2017). "First, EGFR overexpressing tumour cells, high levels of STAT3 activity, loss of caveolin-1, Akt- and Myc- driven tumour cells, and argininosuccinate synthetase enzyme deficiency are all associated with a high autophagy dependency and are therefore more sensitive to CQ administration." (PMID 29225688, 2017). "The hallmark of HNSCC tumour cells is an imbalance in STAT1/STAT3 signalling." (PMID 28315228, 2017). "STAT3 inhibition can attenuate body weight and muscle mass loss in tumor-bearing mice." (PMID 28785374, 2017). "Thus, tumor cell-specific NFκB and STAT3 signalings appear to be required for inflammation-associated tumor initiation in the colon, likely by inducing the expression of pro-proliferative, anti-apoptotic and immune response genes." (PMID 27582544, 2016).
tumor (continued). "Additionally, overexpression of Grim19 has a therapeutic effect on cancer by reducing STAT3 signaling; in contrast, Grim19 deficiency accelerates tumor development by increasing the expression levels of STAT3-responsive genes." (PMID 27258062, 2016). "However, elevated p-STAT3 (OR = 2.45, 95% CI = 1.73 to 3.46, P < 0.00001) expression in tumor tissue seemed to be more significantly associated with worse 3-year OS than STAT3 expression (OR = 1.72, 95% CI = 1.10 to 2.70, P = 0.02)." (PMID 26959884, 2016). "Total STAT3 tumour cell expression was associated with CSS (P<0.001)." (PMID 27769057, 2016). "To test this premise, we examined the consequence of Stat3 loss on tumor vasculature." (PMID 27589562, 2016). "Given the alterations to growth rate of the tumor and the selective pressure to maintain Stat3 expression, we hypothesized that loss of Stat3 may result in alterations to the morphology of the tumors." (PMID 27589562, 2016). "Importantly, phosphorylation of Src and Stat3 have been reported to be upregulated in clinical samples and associated with poor prognosis as well as tumor recurrence." (PMID 27419630, 2016). "Additionally, administration of m28-RNLS to nude mice bearing A375.S2 xenografts caused a 70% reduction in tumor volume, and a >90% decreases in STAT3 activation." (PMID 26972355, 2016). "Considering that the inhibitory effects of GRIM-19 on STAT3 activation may be tumor or cell type-dependent, we investigated whether disturbed STAT3 is involved in GRIM-19 loss-driven GC tumorigenesis in GC." (PMID 27167343, 2016). "Thus, it is plausible that Stat3 activates DNA repair pathways to repair DNA damage caused by Myc, thereby delaying tumor onset." (PMID 27589562, 2016). "It has been reported that STAT3 signaling regulates the IL-12/IL-23 balance, which directs the transcriptional activation of the IL-23/p19 gene and inhibits IL-12/p35 gene expression in tumor-associated DCs." (PMID 26745884, 2016). "Finally, we subcutaneously injected 1 × 106Stat3 knockout or WT cells into BALB/c nude mice, and observed attenuated tumour expansion upon Stat3 deficiency." (PMID 27553854, 2016). "When STAT3 expression was ablated in the hematopoietic compartment using the STAT3fl/fl–Mx1-Cre system, the levels of macrophage-derived IL-23 was greatly reduced and tumor-associated DCs secreted increased amounts of IL-12." (PMID 27148255, 2016). "The signal transducer and activator of transcription 3 (STAT3) also plays crucial roles in the regulation of the cellular processes associated with cancer growth and progression including proliferation, angiogenesis, tumor cell survival and immune function." (PMID 31656694, 2016). "Similarly, a short hairpin RNA (shRNA) targeting the tolerogenic molecule STAT3 encoded by Salmonella also increased apoptosis in tumors of treated mice, enhancing tumor-specific killing of tumor targets." (PMID 27190519, 2016). "High expression level of STAT3 was also associated with advanced tumor stage." (PMID 26959884, 2016). "Moreover, that elevated ph-STAT3 expression was significantly associated with better survival, suggesting a protective role of STAT3 against tumour necrosis." (PMID 27769057, 2016). "Augmented tumor growth with Stat3+/+ B cell adoptive transfer was associated with increased tumor angiogenesis in vivo by Matrigel assay and in vitro in B cell: endothelial cell co-culture assays, and increased expression of pro-angiogenic genes by RNA in vivo." (PMID 27437104, 2016). "Furthermore, Stat3 activity in human tumor tissues was associated with increased density of TIL-B cells and significantly increased intratumoral angiogenesis." (PMID 27437104, 2016). "Stat3 pathway is tightly associated with tumor invasion, metastasis, and angiogenesis in cancers." (PMID 27460364, 2016). "CD5+ B cells have also been implicated in the suppression of anti-tumor immunity in humans through activation of Stat3, a transcription factor that may be involved in production of IL-10." (PMID 27437104, 2016).
tumor (continued). "However, STAT3 negatively regulates NK activation and tumor cell killing, as STAT3-deficient NK cells generally exhibit enhanced cytolytic activity and cytokine secretion in vitro and in vivo." (PMID 27148255, 2016). "In summary, our demonstration of the important roles of the BRG1/STAT3/VEGFC in tumor-associated lymphangiogenesis might lead to the discovery of novel therapeutic targets in the treatment of cancers with BRG1 loss of function." (PMID 27145366, 2016). "Therefore, the idea emerged that STAT3 function is context-dependent either with regards to the oncogenic driver mutation, cancer type or the specific tumour microenvironment." (PMID 25734337, 2015). "Of these, STAT3 is the most well characterized and has been linked to tumor progression." (PMID 26125440, 2015). "Antral tumor development in gp130757FF mice is caused by IL-11-dependent hyperactivation of STAT3, so we tested whether the cardiac stomach lesions of gp130757FF xIL-1RT1−/− mice also developed as a result of IL-11-induced STAT3 phosphorylation (pSTAT3)." (PMID 25528766, 2015). "However, such blockade has no impact on the HER2, HER4, and JAK/STAT pathways, in which activation of STAT3 is associated with tumor growth." (PMID 25674538, 2015). "As most cases of feline OSCC are diagnosed at an advanced stage, our results may support loss of STAT3 activation with tumor progression although further work is needed to investigate the expression of STAT3 in early tumorigenesis." (PMID 26272737, 2015). "STAT3 activation is implicated in tumor progression and angiogenesis." (PMID 26317647, 2015). "Thus, most likely, Stat3-deficient tumours need additional hits to become invasive and to metastasize." (PMID 25734337, 2015). "Moreover, combined loss of p14ARF and STAT3 expression in tumours of PCa patients predicted the worst outcome (P=0.000007, log-rank test)." (PMID 26198641, 2015). "Interestingly, heterozygous loss of STAT3 within the tumours (Stat3ΔLep/+:KrasG12D/+) led to the same drastic phenotype as observed in Stat3ΔLep/ΔLep:KrasG12D/+ animals with a median survival of 108 days." (PMID 25734337, 2015). "All six of the detectable factors are pro-angiogenic and activate STAT3, an oncogene and survival factor that can be activated by many additional cytokines and growth factors, that has been implicated in promoting tumor angiogenesis and modulating the TME." (PMID 25762644, 2015). "Both Dp44mT and DpC could also inhibit IL-6-induced phosphorylation and nuclear translocation of STAT3, which has been implicated in tumor progression." (PMID 26125440, 2015). "Importantly we also demonstrate that loss or inhibition of STAT3–ARF signalling enables tumour progression and metastasis formation." (PMID 26198641, 2015). "Overexpression of STAT3 rescued the loss of tumor angiogenesis caused by miR-874." (PMID 25596740, 2015). "In situ hybridization not only corroborated the increased expression of Cxcl1 in Stat3-deficient tumours but also identified the tumour cells as the main cellular origin of Cxcl1 as confirmed by staining for the alveolar type 2 cell-specific marker SP-C (surfactant protein C) in serial sections." (PMID 25734337, 2015). "In addition, blocking of EGFR/HER1 has no impact on the HER2, HER4, and JAK/STAT pathways (by-pass signaling pathways), in which activation of STAT3 is associated with tumor growth and malignancy." (PMID 25674538, 2015). "By modulating STAT3 associated immune response in tumor microenvironment, the negative regulatory loop between miR-17 and STAT3 may be an important factor in tumor-associated immune tolerance and a potential immunotherapeutic target against cancer." (PMID 25594054, 2014). "STAT3 activation is also associated with tumor survival and therapeutic resistance." (PMID 24743777, 2014).
tumor (continued). "Indeed, evading detection and clearance by innate and adaptive immune cells is a hallmark of cancer and STAT3 plays equally important roles in regulating leukocyte cell function as it does in tumor cells, putting it at the crossroads of tumor immune evasion." (PMID 24722453, 2014). "Several subsequent studies also have implicated STAT3 in the context of tumor immuno-surveillance." (PMID 24995504, 2014). "To explain how STAT3 may mediate its tumor suppressor effects, we will discuss several possible mechanisms, one of which is linked to the role of STAT3β, one of the two STAT3 splicing isoforms." (PMID 24995504, 2014). "In STAT3-deficient mice, the liver tumour load caused by DEN treatment was significantly reduced." (PMID 24708807, 2014). "Quite recently, Yang and colleagues identified the interplay between B cells with ECs via the signal transducer and activator of transcription 3 (STAT3) an established and critical mediator of tumor angiogenesis caused by its potential to regulate VEGF expression." (PMID 24782982, 2014). "In addition, STAT3 signaling modulates tumor growth and metastasis via recruitment of tumor-associated macrophages (TAMs) to the tumor site." (PMID 24886617, 2014). "Importantly, production of angiogenic factors such as VEGF and bFGF by TAMs are induced by Stat3, and experiments with mice deficient for Stat3 in the myeloid compartment, showed that it is a crucial mediator for myeloid cell-induced tumor angiogenesis." (PMID 24723924, 2014). "However, it has become clear that signal transducer and activator of transcription 3 (STAT3) is a kind of master switch that is connected to most signalling pathways related to both oncogenesis and tumor-associated inflammation." (PMID 25149535, 2014). "Adoptive transfer of intrinsic activated STAT3-expressing B lymphocytes into implanted Rag1−/− mice, lacking mature T or B cells resulted, contributed to tumor growth and progression whereas in turn, adding STAT3-deficient B cells to the tumor microenvironment resulted in reduced tumor development." (PMID 24782982, 2014). "STAT3 is associated with tumor progression in many malignant tumors." (PMID 24738052, 2014). "Furthermore, cross-talk between tumor stroma and tumor epithelial cells that promotes CSC phenotypes required STAT3 signaling within the tumor associated fibroblasts." (PMID 24675570, 2014). "As a member of the STAT family, STAT3 plays a significantly important role in human cancers, and is closely associated with the proliferation and apoptosis of tumor cells in a wide variety of tumor types." (PMID 24959290, 2014). "This positive feedback loop was found in both tumor cells and tumor-associated stromal cells, and the IL-6 produced by these two types of cells mediates the crosstalk between them, and enables a persistent activation of STAT3 in both cell types." (PMID 24995504, 2014). "To identify the molecular events underlying Stat3+/+ B cell-driven tumor angiogeneisis, we assessed whether tumor-associated B cells themselves expressed pro-angiogenic factors in a Stat3-dependent manner." (PMID 23734190, 2013). "Furthermore, recent studies also showed that the constitutive activation of STAT3 propagated the change from tumor cells to tumor-associated immune cells within TME, such as TAMs, DCs, NK cells, neutrophils and lymphocytes." (PMID 23825527, 2013). "Alternatively, IL-17 has been shown to induce IL-6 production from tumor cells and tumor-associated stromal cells, which in turn activate STAT-3, an oncogenic transcription factor that upregulates pro-survival and pro-angiogenic gene levels in transformed cells." (PMID 23533029, 2013). "Furthermore, IL-6–silencing vectors significantly inhibited TRAMP-C1 and HR tumor regrowth and invasion, which was associated with attenuated expressions of angiogenic factors and STAT3 activation." (PMID 23806095, 2013).
tumor (continued). "Nanog, Stat-3 and miR-21 could form a functional signaling axis that provides therapeutic targets to cause tumor cell apoptosis and overcome cisplatin chemoresistance." (PMID 23467648, 2013). "We also found that IL-6 secreted by tumor-associated fibroblasts could upregulate STAT3 activation in NPC cells in culture." (PMID 24380387, 2013). "These mice display low but continuous STAT3 activity in all tissues, which led to accelerated oncogene-mediated breast tumourigenesis and increased metastasis, altered energy metabolism and predisposition to tumour transformation." (PMID 23460527, 2013). "Both STAT-1 and STAT-3 signaling have been implicated in tumor development." (PMID 24216992, 2013). "As in residual cells, the role of Il-6/Stat3 in tumor dissemination may be linked to activation of cell growth and survival pathways." (PMID 23520493, 2013). "Moreover, it is known that the STAT3 Ser-727 is phosphorylated by ERK1/2 and that STAT3 is also implicated in the proliferation tumor-derived cell lines." (PMID 23902727, 2013). "Furthermore, the differences in tumor growth caused by Stat3 activity in B cells were accompanied by differential intensities of tumor angiogenesis." (PMID 23734190, 2013). "Furthermore, up-regulation of IL-22 in TILs derived from human CC was associated with the activation of STAT3 and exhibited tumor promotion and enhancement of metastasis in both in vitro and in vivo model." (PMID 23379788, 2013). "Cumulatively, these data indicate that tumor-associated hypoxia may induce STAT3 during the initiation of antiangiogenic therapy but certainly other mechanisms are involved." (PMID 23013619, 2012). "However, in certain cell types such as PTEN-deficient glioblastoma, STAT3 can become a tumor suppressor." (PMID 22423663, 2012). "Increase in STAT3 signal fitness through oncogenic events and/or tumor-associated extrinsic signals such as IL-6 may be partially driven through APE1." (PMID 23094050, 2012). "However, the HCV core protein itself was also implicated as tumor initiator inducing proliferation, anti-apoptosis and oxidative stress-related DNA adducts by activation of c-jun and stat-3." (PMID 22792259, 2012). "This should alleviate the systemic toxicity associated with total 14-3-3ζ or Stat3 inhibition and retain most of their functions but may affect tumor growth." (PMID 22279540, 2012). "Finally, STAT3 has been shown to be a key defining feature responsible for the polarization of the tumor-associated macrophage to the tumor supportive M2-phenotype." (PMID 23013619, 2012). "In vivo, STAT3 inhibitors can also decrease cancer-associated inflammation, suggesting that targeting leukocyte STAT3 in the tumor microenvironment may be a therapeutic option that will be applicable in the future." (PMID 22136659, 2011). "To test the hypothesis that constitutively activated STAT3 has a causal role in suppressing Necdin expression in tumor cells, we examined whether transient activation of STAT3 signaling could down-regulate Necdin expression." (PMID 22046235, 2011). "STAT3 has also been implicated in tumor invasion and suppression of apoptosis." (PMID 22190972, 2011). "Decreased tumor-associated inflammation induced by STAT3 inhibitor may be a secondary response after the inhibition of STAT3 in tumor cells." (PMID 22136659, 2011). "STAT3 and pSTAT3 expressions were significantly associated with grade of the tumor (P < 0.001)." (PMID 21575192, 2011). "However, STAT3 and pSTAT3 expressions were significantly associated with grade of the tumor (P < 0.001)." (PMID 21575192, 2011). "Thus, activation of IL-10/STAT3 can impair autophagy induction and decrease autophagy-associated tumor cell death." (PMID 21931823, 2011). "STAT3 and cMyc have also been implicated in both primary tumor growth as well as tumor metastasis." (PMID 21541295, 2011).